MYC (MYC proto-oncogene, bHLH transcription factor)
Diseases named in the same sentence as MYC in open-access papers (continued):
Sharing a sentence is not in itself a finding about the gene and the disease.
tumor (continued). "Moreover, oncogenic activation of MYC and/or loss of a MYC antagonist, results in an imbalance in the activity of the network as a whole, leading to tumor initiation, progression and maintenance." (PMID 30054853, 2018). "Furthermore, genes involved in cyclin D, mTOR, and Ras signaling were downregulated following MYC knockdown, suggesting that MYC expression was closely associated with tumor cell growth." (PMID 30524948, 2018). "While MYC overexpression can have a dominant impact on a host of genes that promote tumor growth, combination of MYC overexpression with concurrent loss or activation of other genes may contribute to aberrant tumor growth in TNBC." (PMID 28696357, 2017). "Importantly, SFN sensitized NSCLC cells to cisplatin's efficacy in vivo, which is associated with inhibition of cisplatin-induced c-MYC accumulation in tumor tissues." (PMID 28076844, 2017). "The MYC transcription factor, overexpressed in most human cancers and associated with highly proliferative tumours and poor prognosis, was found to regulate the maintenance of a fully functional splicing machinery by controlling the transcription of snRNP components." (PMID 28374191, 2017). "The observed variability in MYC expression levels among tumor cell lines with KRAS mutations prompted us to investigate whether MYC plays a role in anticancer drug resistance." (PMID 28152508, 2017). "PBMR1 mutant tumours are associated with increased activity of TFs/(phospho)proteins that have roles in interleukin signalling and MYC, while regulators with increased activity in BAP1 mutant tumours are involved in DNA damage response, apoptosis, insulin signalling and mTOR signalling." (PMID 28139702, 2017). "Furthermore, MYC over-activation can induce genomic instability, a process linked to tumor initiation." (PMID 28333115, 2017). "Importantly, very high levels of MYC expression (upper quartile, > 421) were associated with a much higher risk of tumor recurrence (HR of 9.4, 95%-CI: 3.2-27.2, P < 0.0001)." (PMID 29100407, 2017). "To elucidate mechanisms underlying STK38L dependency in PDAC cell lines, we characterized the effects of STK38L depletion on expression levels of key proteins in KRAS and general tumor-associated signaling pathways including p21, MYC, MAPK, PI3K, and autophagy." (PMID 29108249, 2017). "In addition, c-MYC protein overexpression was associated with a tumor location in the recto-sigmoid colon." (PMID 27619912, 2016). "Based on the relevance of deregulation of MYC family members in SCLC, we hypothesized that SCLC models would be more susceptible to BRD inhibition/MYC gene downregulation than other tumor types." (PMID 27835869, 2016). "We further demonstrate that inhibition of this newly defined MYC effector pathway causes robust and selective tumor cell apoptosis, via an acute, checkpoint-like mechanism linked to aberrant electron transport chain complex assembly and mitochondrial reactive oxygen species (ROS) production." (PMID 27590350, 2016). "On the basis of these findings, we focused on tumour types associated with c-MYC hyperactivation." (PMID 26729287, 2016). "c-MYC promotes cellular proliferation and mutations, which can lead to neoplasia." (PMID 27007654, 2016). "A tumor may critically depend on the activated c-MYC so that switching it off, as shown in transgenic mouse models, causes tumour regression." (PMID 27655693, 2016). "Inactivation of c-MYC causes rapid tumor regression in mouse model, indicating that targeting c-MYC itself might be an effective therapeutic strategy for this disease." (PMID 27775567, 2016).
tumor (continued). "Taken together, we propose that this MYC-amplification associated glycolytic phenotype may confer a powerful growth advantage and influence the aggressive behavior of this tumor subtype." (PMID 25970789, 2015). "The tumor harboring a PLCG1 R707Q mutation also harbored a MYC amplification." (PMID 26440310, 2015). "However, ≥ 3.0 c-MYC copies/nucleus in the primary tumor was significantly associated with a poor prognosis (P = 0.044)." (PMID 26426996, 2015). "It is well known that MYC dysregulation has the ability to affect gene regulation, microRNA expression profiles, large genomic amplifications and ultimately initiates a dynamic process of genomic instability that is linked to tumor initiation." (PMID 26517511, 2015). "The aim of this study was to test the hypothesis that inhibition of HUWE1is feasible to control MYC activity in this tumor entity and to explore the underlying mechanisticbasis." (PMID 25253726, 2014). "Furthermore, we observed that MYC immunoreactivity and increased mRNA expression were associated with deeper tumor extension and presence of metastasis." (PMID 23717612, 2013). "Additionally, increases in MYC expression was associated with tumor progression and poor cancer-specific outcome within this patient population." (PMID 24077122, 2013). "In addition, MYC amplification by FISH was associated with advanced tumor stages (p = 0.037; η2 = 0.091, OP = 0.558), however, only two early tumors were analyzed in this subset of samples." (PMID 23717612, 2013). "In addition, we demonstrated that MYC hypomethylation was associated with a more aggressive phenotype (tumor aggressiveness, presence of lymphnode metastasis, and histological types of cancer)." (PMID 23717612, 2013). "Via IPA, ESR1 and NFkB were linked to developmental disorder, reproductive system disease, cellular growth and proliferation; MYC was linked to cancer, infection mechanism, gene expression and tumor morphology; and ERK1/2 was linked to molecular transport, protein trafficking and cell cycle." (PMID 22616791, 2012). "The six common PTEN-controlled TFAs including c-MYC most likely play an essential role in tumor development caused by PTEN loss and their activity may serve as surrogate markers for determining PTEN functional status and measuring response to targeted therapy." (PMID 22347425, 2012). "MYC controls numerous genes involved in stem cell functions, differentiation, growth, immortalization, metabolism, survival and other fundamental cellular processes, and deregulated expression of MYC is very often implicated in human tumor development including hematological malignancies." (PMID 22393362, 2012). "Transcriptional activation of MYC is a hallmark of many B cell lineage neoplasms." (PMID 22754359, 2012). "Hence withdrawal of MYC can lead to tumor regression associated with tumor cell death, senescence and/or differentiation." (PMID 22132187, 2011). "Several studies of tumor formation in in vitro and in vivo systems with conditional MYC expression have demonstrated that MYC induction promotes tumor formation while its down-regulation causes tumor cell growth arrest, enhanced apoptosis, senescence, tumor regression and/or differentiation." (PMID 22132187, 2011). "Furthermore, two studies have demonstrated that high c-MYC mRNA expression is associated with tumor anaplasia." (PMID 19134217, 2009). "Furthermore, high c-MYC mRNA expression was demonstrated to be significantly associated with tumor anaplasia." (PMID 17254356, 2007). "Understanding the interplay between genomic instability, MYC dosage compensation, and the underlying interactions with the miRNA-17/92 not only sheds light on cancer pathogenesis but also highlights potential therapeutic targets to disrupt these compensatory mechanisms and impair tumor growth." (PMID 40940795, 2025).
tumor (continued). "MYC can enhance cell reprogramming efficiency by regulating cell metabolism during early reprogramming stages through the induction of a robust hybrid energetics program, although it has been shown to be associated with the promotion of undesired tumor formation." (PMID 39988676, 2025). "Thus, MYC may exaggerate whatever programs are triggered by other oncogenes and this oncogenic impulse is abetted by mutations inactivating tumor suppressors." (PMID 40970130, 2025). "This is consistent with a report identifying HEATR1, as well as MYC (see discussion below), as the highest scoring genes among a group of 68 ribogenesis-associated factors screened for ability to promote rRNA synthesis in a normal (non-tumour) breast cell line." (PMID 38225354, 2024). "Reports suggest that MYC overexpression can cause tumorigenesis, contributing to many of the hallmarks of cancer, including proliferation, self-renewal, cell survival, genomic instability, metabolism, invasiveness, angiogenesis, and remodeling of the tumor microenvironment." (PMID 38277205, 2024). "However, MYC is also implicated in multiple other tumor forms." (PMID 36969025, 2023). "The activation of MYC in Fh1-deficient cells, which was previously hypothesized, led to increased expression of the karyopherin subunit alpha 2 (Kpna2), a nuclear transporter involved in the nucleocytoplasmic transport of several tumour-associated factors." (PMID 37689804, 2023). "To study the cellular mechanism associated with the increased tumor load in miR-32 overexpressing prostates, we studied whether transgenic miR-32 expression affects the rates of proliferation, mitosis, or apoptosis in the MYC-induced adenocarcinoma." (PMID 35228520, 2022). "Furthermore, the compound inhibits tumor cells proliferation in the athymic xenograft mice model, without any apparent toxicity yet suppressing the expression of Wnt target genes associated with tumor growth, including MYC (c-myc), CCND1 (cyclin D1), and BIRC5 (survivin)." (PMID 35053565, 2022). "Some of those genes are related to positive regulation of cell cycle, cell differentiation, and apoptotic process, indicating that eucalyptol may be implicated in its anti-tumor effects by down-regulating MYC and its target genes involved in cell division, differentiation, and apoptosis pathways." (PMID 36331666, 2022). "Although such transcriptomic changes could be due to the decreased presence of immune cells in bulk tumor samples, these immune pathways were also downregulated in sorted tumor cells, indicating that MYC-associated immune evasion is mediated by a tumor cell-intrinsic mechanism." (PMID 36323660, 2022). "To test whether the observed up-regulation of DNMT1 expression in ALK tumor samples is associated with deregulation of cell cycle–associated genes, we performed Western blot analysis using antibodies against c-MYC, CDK4/CDK6, cyclin D1, and the proliferation marker PCNA." (PMID 33310759, 2021).
tumor (continued). "In this view, it will be interesting to evaluate whether MYC‐driven tumours, which are known to be particularly susceptible to spliceosome inhibition, are also particularly sensitive to the anti‐tumoral activity of CLK inhibitors and whether these drugs synergise in combined regimens." (PMID 34092037, 2021). "Moreover, high CDK7 expression, high MYC expression, and low tumor-infiltrating lymphocytes (TILs) could serve as three risk factors to differentiate NSCLC patients with different survival outcomes." (PMID 32690037, 2020). "Our mechanistic analysis of the successful targeting of these two pathways, which induced synergistic anti-tumor activity in susceptible tumors, identified MYC as an important upstream driver regulated by the combined pathways through their cooperative effects on MYC protein degradation." (PMID 32923678, 2020). "MYC and Twist1 cooperate and their sustained expression is required to elicit a transcriptional program associated with the activation of innate immunity, through secretion of a cytokinome that elicits recruitment and polarization of tumor associated macrophages (TAMs)." (PMID 31933479, 2020). "In breast cancer cells, exosomal (mi)RNA released by cancer-associated fibroblasts enhance tumor growth, metastasis, and therapeutic resistance; whereas cancer cells-derived exosomal miR-105 promotes tumor growth through MYC proto-oncogene (MYC)-dependent metabolic reprogramming of stromal cells." (PMID 33297544, 2020). "Thus, the detection of MYC-positive macrophages is associated with increased tumor growth." (PMID 32523087, 2020). "Rather, sequestration of SPT5 by oncogenic levels of MYC decreases Pol II processivity and directionality on genes that are known targets of MYC-dependent repression, for example genes encoding proteins of the TGFβ pathway and regulators of the interactions of tumor cells with the immune system." (PMID 30928206, 2019). "The preceding analysis indicates that given such a biological process involves functional tumor associated genes, such as cadherin family, p38, and MYC, we can reasonably speculate that the genes that participate in such a biological process are highly expressed." (PMID 30595815, 2019). "Indeed, further genotyping a patient’s tumor for MYC mutations, or ideally ODC overexpression, may improve clinical success of DFMO even more." (PMID 29419804, 2018). "As MYC is closely associated with tumor aggressiveness such as self-renewal capacity, proliferation and epithelial to mesenchymal transition, we hypothesize that this newly identified interaction might lead to early initiation and finally to tumor progression in our model." (PMID 29383100, 2017). "In conclusion, using an in vitro model of hypoxia, susceptible to mimic more closely the in vivo hypoxic tumor conditions, we depicted metabolomic profiles of response to the combination of rapamycin plus irinotecan, determined by a balance between upstream signals in MYC and mTOR/HIF-1/2α pathways." (PMID 29069732, 2017). "Finally, we attempted to assess whether VHL loss, CDKN2A loss and MYC activation are dysregulated at tumour initiation or tumour progression, by analysing their relative frequency by TNM stage in the TCGA KIRC data set." (PMID 28593993, 2017). "Collectively, these results demonstrate that MYC-overexpressing cells are dependent on proper expression of mitochondrial encoded proteins for cell survival, a dependency that can be exploited using antibiotics to selectively induce the death of tumor cells expressing oncogenic levels of MYC." (PMID 27590350, 2016).
tumor (continued). "In addition, MYC hypomethylation was associated with advanced tumor stages (p = 0.033; OR = 6.602; 95% CI = 1.162–37.501), deeper tumor extension (p = 0.022; OR = 4.752; 95% CI = 1.257–17.965), and the presence of lymph node metastasis (p = 0.032; OR = 5.12; 95% CI = 1.149–22.814)." (PMID 23717612, 2013). "Nuclear PFKM interacts with c-MYC, which upregulates the expression of carnitine o-palmitoyltransferase 1 muscle isoform (CPT1B) to activate FAO, thereby sustaining tumor cell survival upon glucose deficiency." (PMID 41818193, 2026). "MCL-1 inhibition downregulates MYC and activates the STAT1-interferon inflammatory pathway, promoting cytotoxic T-cell infiltration with reduced tumor-associated myeloid cells both in vitro and in vivo." (PMID 41680300, 2026). "For instance, liver tumours require substantial amounts of tryptophan to synthesise the oncogenic metabolite indole‐3‐pyruvate, and MYC induction is pivotal to tryptophan involvement in HCC tumour metabolism." (PMID 40504108, 2026). "This ARMC12-MYC interplay propels tumor growth and enhances aggressiveness, underscoring the pivotal role of the ARMC12/MYC axis in driving NB progression." (PMID 41510169, 2026). "Upregulation of the oncogene MYC has been demonstrated in SebCA, suggesting a role in tumor initiation and progression." (PMID 41898225, 2026). "Specific inhibitors of IL-17RA signaling, such as the STAT3 inhibitor Stattic, reduced the expression of CD133, LGR5, ALDHA1, SOX2 and c-MYC, as well as tumor sphere formation in SW620 cells." (PMID 41438576, 2026). "Levels of total-, phosphorylated- (Ser552) and active β-catenin (i.e. unphosphorylated at Ser33/Ser37/Thr41) as well as the downstream target gene (c-MYC) were also reduced in RSPO4-expressing tumor cells compared with vector control cells." (PMID 41522353, 2026). "MYC, a well-known oncogene, is regulated by multiple upstream enhancers and plays a central role in tumor initiation and progression, making it an ideal target for chromatin architecture studies." (PMID 41251144, 2026). "In both primary and metastatic tumours, the overexpression of MYC is correlated with suppression of STING, contributing to resistance against immune checkpoint blockades (ICBs)." (PMID 41492185, 2026). "This review highlights MYC as a master regulator of tumor-immune interactions and underscores the therapeutic potential of MYC inhibition to overcome resistance and expand the clinical impact of cancer immunotherapy." (PMID 41659859, 2026). "Paradoxically, c-MYC also exhibits intrinsic tumor-suppressive activity through apoptosis, a phenomenon known as the "c-MYC paradox"." (PMID 41959199, 2026). "RESULTS: The number of MYC-amplified tumor cells varied largely ranging from few scattered single cells (< 20 per high power field) up to all tumor cells." (PMID 42032556, 2026). "MYC promotes uncontrolled proliferation of tumor cells by activating cyclin-dependent kinase 4 in cell cycle S-phase entry 40 and fuels metabolic reprogramming via aerobic glycolysis or biosynthetic intermediate production." (PMID 41510169, 2026). "For example, PTEN and CASP8 act as tumor suppressors, whereas STAT3, MYC, EGFR, and TGFB1 are canonical oncogenic drivers implicated in cell cycle progression, stemness, and therapy resistance, particularly in triple-negative BC." (PMID 41596512, 2026). "We also examine how transcriptional and oncogenic regulators, including SOX2, MYC, and androgen receptor signalling, reprogramme sialyltransferase expression to produce tumour-specific sialoglycan profiles." (PMID 42132142, 2026). "miR-4652-3p suppressed glutamine metabolism in NSCLC cells by negatively regulating the MYC/SLC1A5 axis, consequently inhibiting cell growth and tumor progression in a xenograft mouse model, an effect reversed by MYC or SLC1A5 overexpression." (PMID 41654992, 2026).